CDK1 (cyclin dependent kinase 1)
Diseases named in the same sentence as CDK1 in open-access papers (continued):
Sharing a sentence is not in itself a finding about the gene and the disease.
cancer (continued). "More recently, the sensitivity of cancer cells to antimitotic drugs has been shown to have a dependence on the ability of cyclin B1/Cdk1 to phosphorylate and increase the degradation of Mcl-1 in order to enhance apoptosis." (PMID 24058878, 2013). "Another potential therapeutic target for cancer treatment is represented by cyclin B1, the regulatory subunit of cyclin-dependent kinase 1 (cdk1), which plays a pivotal role in the transition of the cell cycle from G2 phase to mitosis." (PMID 23835136, 2013). "This identified many genes, including CylinD1/D3, Cdk1/2, Psme3, Rad52/54L and Skp2 that have previously been shown to be dysregulated in cancer." (PMID 23762407, 2013). "For example, cyclin-dependent kinase 1 (CDK1), polo-like kinase 1 (PLK1), and cancer susceptibility candidate 5 (CASC5) took part in the regulating proliferation of CAF itself and tumor cell." (PMID 23577100, 2013). "Eight proliferation-associated genes including CCND1, CDK1, CDK6 and 26 apoptosis-regulating genes (e.g. SOCS3) were differently expressed between juvenile and cancer groups mostly supporting the pronounced cell growth in CRC." (PMID 24098334, 2013). "Thus, by allowing a small window towards mutagenesis and genome rearrangements, which in long term could be advantageous to both cancer cells and evolution, the Cdk1/Cdc5/Mus81-Mms4 pathway protects against more severe loss of information, which in short term would endanger cellular life." (PMID 23531881, 2013). "Here we found several proliferation promoting genes including cyclin B1 /CCNB1/, cyclin E1 /CCNE1/ and cyclin-dependent kinase (CDK1) to be upregulated both in young and cancer samples compared to normal adult mucosa." (PMID 24098334, 2013). "It has been indicated that over-expression of CDK1 is common in DLBCL cancer types, and it is therefore a potential therapeutic target." (PMID 22427814, 2012). "Recently, it was also demonstrated that CDK1 inhibitors can be used in combination with PARP inhibitors to selectively kill cancer cells and spare normal cells." (PMID 24970153, 2012). "In an attempt to discover natural compounds that disrupt G2 checkpoint in cancer cells, we used genistein, an inhibitor of cdk1 phosphorylation." (PMID 23351311, 2012). "Cdk1 and Cdk4 have been shown to have closely correlated expression across a wide range of human cancer cell lines." (PMID 21668989, 2011). "Among the key changes in the cell cycle in normal to cancer transition are the differential expression of cyclins (A and B) and cyclin-dependent kinases (CDK1 and CDK4/6 complex)." (PMID 20875095, 2010). "Oncogenes such as MYC, AKT1, AKT2, cyclins CCNA2, CCNB1, CCNB2, CCNE1, CCNE2 and cyclin-dependent kinases CDK1 and CDK4, which were upregulated under androgen treatment, exhibited a significantly reduced expression following PVT1 knockdown, thereby modulating cancer-associated oncogenic pathways." (PMID 41792045, 2026). "Additionally, K was found to induce G2/M phase cell cycle arrest, accompanied by a decrease in the expression levels of cyclin B and CDK1 in treated cancer cells." (PMID 40830621, 2025). "Although CDK1 may be a promising target for cancer therapy, its mechanisms and importance in carcinogenesis and cancer treatment are unelucidated." (PMID 39991589, 2025). "Additionally, the top hub genes identified in the PPI network of FZD4 miRNA targets, including MYC, EGFR, MDM2, and CDK1, were also involved in many aspects of cancer progression." (PMID 40667070, 2025). "Conversely, the positive interaction of SPAG5 with CDK1 may enhance cell cycle progression, potentially contributing to uncontrolled cell proliferation during cancer development." (PMID 39762615, 2025).
cancer (continued). "CDK1, as a key regulator of the cell cycle, not only plays a vital role in cancer cell proliferation but may also be critical in renal cell stress responses induced by chemotherapy and radiotherapy." (PMID 39911265, 2025). "The direct application of CDK1 inhibitors in the treatment of cancer is being gradually explored." (PMID 40332418, 2025). "Here, we show that CDK1, cyclinA2 and cyclinB1 are expressed at increased levels in invasive BC cells in comparison to non-invasive cells, therefore identifying the regulatory mechanisms that control CDK1 and cyclin expression in cancer is paramount." (PMID 40518827, 2025). "Furthermore, when ROS inhibited the phosphatase CCNB1, leading to the activation of CDK1, it promoted the cycle progression of cancer cells." (PMID 40183046, 2025). "Furthermore, phosphorylation of ULK1 and its binding protein by cyclin-dependent kinase 1/cyclin B promotes mitotic entry and cell cycle progression, as indicated by impaired cancer growth upon genetic deletion of ULK1 or ATG1367." (PMID 41408407, 2025). "Previous studies have demonstrated the inhibitory effects of compounds such as Alsterpaullone, Fostamatinib, Olomoucine, and Seliciclib on CDK1 activity, while agents like Adavosertib and Fostamatinib target WEE1, thereby indirectly modulating CDK1 activity and inhibiting cancer progression." (PMID 41009727, 2025). "Additionally, the overexpression and dysregulation of CDK1 in human cancers support targeting CDK1 as a potential therapeutic." (PMID 41463161, 2025). "It works by disrupting a key protein named CDK1 that helps cancer cells divide." (PMID 40282517, 2025). "Additionally, it targets oncogenic mRNAs, including CD44 and CDK1, and leads to reduced proliferation and migration in various cancers." (PMID 41388527, 2025). "CDK1 inhibitors are potential effective anti-cancer small-molecule drugs." (PMID 40657363, 2025). "Moreover, ZWINT is directly regulated by CDK1 in many cancer types, and related to cancer cell metastatic ability through CDK1/ZWINT-mediated epithelial-mesenchymal transition (EMT) process." (PMID 40591167, 2025). "The functional pathway of CDK1 was examined as a primary target for anti-cancer drug development." (PMID 41009727, 2025). "Podophyllotoxin can significantly inhibit the growth and spread of cancer cells by blocking the normal cell cycle through inhibiting PLK1/CDK1 and suppressing the expression of EMT-related proteins (e.g., N-cadherin, MMPs), but its development has been limited by high toxicity and other drawbacks." (PMID 41050074, 2025). "Additionally, network analysis showed that cyclin-dependent kinase 1 (CDK1) was encountered in the mechanism of action of the three cancer types." (PMID 38319945, 2024). "Targeting CDK1 has been identified as a promising therapeutic approach for treating cancer." (PMID 38895552, 2024). "Recent research has also highlighted the importance of CDK1 in other cellular processes, such as transcription, epigenetic control and stem cell self-renewal, which may contribute to its role in cancer initiation and spread." (PMID 38891892, 2024). "Consequently, targeting abnormal CDK1/2 expression and activity has emerged as a promising therapeutic strategy to suppress cancer cell proliferation and restore proper cell cycle regulation." (PMID 38606093, 2024). "Drugs targeting the ATR-Chk1-Wee1 pathway and CDK1 may thus be key strategies for the treatment of malignant tumors." (PMID 39464635, 2024). "In recent years, CDK1 has been suggested as a therapeutic target for cancer." (PMID 38605349, 2024). "In addition, ROS can interfere with the function of the phosphatase Cdc14B, leading to the activation of cyclin-dependent kinase 1 (Cdk1), which facilitates the progression of the cancer cell cycle." (PMID 38338912, 2024). "The significant presence of CDK1 in several types of cancer highlights its potential as a target for creating new cancer therapies that may be widely applied." (PMID 38895552, 2024).
cancer (continued). "Last but not least, all the regulatory enzymes discovered in this study, including USP34, Pin1, Plk1, CDK1 and Ubc9, could be effective drug targets for combination therapies to treat GBMs and potentially other malignant tumors." (PMID 38167292, 2024). "Future studies may discover more inhibitors for CDK1 and Pin1 to achieve the combination therapy for cancer treatment." (PMID 38167292, 2024). "These CHs exert anti-inflammatory, anti-angiogenesis, apoptosis, and cell cycle arrest activities in cancer cells through a wide range of molecular mechanisms such as cyclin-dependent kinase 1 (CDK1), proliferating cell nuclear antigen (PCNA), and nuclear transcription factor kappaB (NFκB)." (PMID 38921023, 2024). "WEE1 kinase is a key gatekeeper of the G2–M transition through inhibitory phosphorylation of CDK1 at the conserved Tyr15 residues and is an effective anti-cancer target, we subsequently examined the expression of WEE1 kinase protein and mRNA levels after SHCBP1 knockdown in three tumour cell lines." (PMID 38365687, 2024). "Aberrant activation and inhibition of CDK1/2 can affect the progression of cancer." (PMID 38093266, 2023). "Cancer cells have dysregulated cell cycle checkpoints, which makes them vulnerable to small molecule inhibitors targeting kinases regulating the essential Cdk1." (PMID 38020882, 2023). "However, there is growing evidence that CDK1 can act as a driver of cancer development and progression." (PMID 37718413, 2023). "Several of the hits in our screen (such as PLK1 and CDK1) have previously been labelled as “core essential”, “fitness genes” or “pan-cancer” genes, as they are considered essential for all cells (cancer and healthy cells) to function." (PMID 37161535, 2023). "CDK1 was reported to play an essential role in the formation and growth of cancer." (PMID 37324186, 2023). "This abundance of evidence clearly supports CDK1 as a promising target for cancer therapy." (PMID 37311884, 2023). "Moreover, we demonstrated that CDK1-wildtype interacted with STAT3, while mutations CDK1-K33R or CDK1-K33Q both impeded the interaction with STAT3, resulting in reduced phosphorylation of STAT3, which caused the diminishment of cancer stemness." (PMID 37743465, 2023). "Studies on the cytotoxic activity of lecanoric acid showed that this depside has moderate activity against colon HCT116 cancer cells and reduced cell colony formation by decreasing Axin2 expression and M phase arrest (downregulation of CDK1, upregulation of cyclinB1 and pH3)." (PMID 36675938, 2023). "Additionally, we examine the current CDK1 inhibitors that have been evaluated in preclinical and clinical studies for cancer therapy." (PMID 37311884, 2023). "Cancer cells promote CDK1 activity, a feature of great interest for targeted cancer therapy." (PMID 37808268, 2023). "In line with its role in ensuring developmental viability, and its nonredundant role in the cell cycle, CDK1 is one of the least mutated CDKs in cancer." (PMID 37718413, 2023). "The upregulation of Tyr15 phosphorylation in cancer may contribute to the dysregulation of CDK1 activity and potentially play a role in the acquisition of resistance to anticancer drugs." (PMID 37898722, 2023). "To test this, we investigated CDK1 activity in relation to expression of NQO1 in cancer cells." (PMID 36793872, 2023). "This review thus far has examined the critical role of CDK1 in cancer." (PMID 37311884, 2023). "Additionally, wogonin inhibits the cell cycle of cancer cell lines by inhibiting the expression of cyclin D1, cyclin B1, and CDK1, inducing apoptosis, improving the Bax/Bcl‐2 ratio, and increasing caspase‐3 cleavage." (PMID 37132286, 2023). "Collectively, these results indicate that targeting CDKs, and especially CDK1, could be a critical strategy for cancer treatment." (PMID 37311884, 2023).
cancer (continued). "Overall, the data indicate that the top 5 CDKs, CDK1 (11/32 or 34.4%), CDK2 (10 /32 or 31.3%), CDK6 (8/32 or 25%), CDK7 (9/32 or 28.1%), and CDK19 (8/32 or 25%), are closely associated with survival probability in various cancers." (PMID 37311884, 2023). "The remainder of this review focuses on mediators, substrates, and inhibitors of CDK1 in cancer." (PMID 37311884, 2023). "The results suggest that CDK1 is a promising target protein in various cancers." (PMID 37311884, 2023). "Thus, several common cancer-associated elements were monitored, demonstrating that the patterns of p-AKT, CDK1, CDK6 and PIK3CA were reduced in response to TMED3 depletion." (PMID 36991473, 2023). "Overall, this review summarized the function and mechanism of CDK1 in cancer." (PMID 37311884, 2023). "For the first time, we demonstrated that CR treatment could inhibit cancer cell growth by inhibiting the PLK1/CDK1/Cyclin B axis across ten cancer cell lines based on gene expression profile analysis." (PMID 37007025, 2023). "CDK1 acts as a kinase that phosphorylates human telomerase reverse transcriptase (hTERT) in T249 during mitosis, which is more common in aggressive and advanced forms of cancer, indicating an additional role of CDK1 in cancer progression." (PMID 38069284, 2023). "The accumulated findings demonstrate that CDK1 could be a potential target for cancer prevention and therapy." (PMID 37311884, 2023). "Next, we focused on the potential regulatory effect of NQO1 on CDK1 in cancer cells." (PMID 36793872, 2023). "Interestingly, oncogenic alterations of CDK1 can be considered rare genetic events, suggesting that complex molecular mechanisms contribute to the aberrant regulation of CDK1 in cancer." (PMID 37898722, 2023). "Emerging evidence supports the important biologic role of CDK1 in controlling the cell cycle in many cancers, and the complexes of CDK1 with cyclin A and cyclin B are sufficient to drive cancer cell cycle progression via the phosphorylation of hundreds of proteins at multiple sites." (PMID 37569750, 2023). "CDK1 triggers the initiation of cytokinesis by inducing the nuclear localization of mitotic cyclins A and B, and its inhibition has been proposed as a cancer therapy with potentially higher efficacy than the inactivation of other CDKs." (PMID 38063302, 2023). "Additionally, tumor suppressors caspase 8 (CASP8) and caspase 9 (CASP9) are phosphorylated by CDK1 facilitating apoptosis in cancer cells." (PMID 37311884, 2023). "CDK1 overexpression can also promote the development and progression of a variety of cancers." (PMID 35681641, 2022). "This association between CDK1 and the tumor microenvironment might be another reason for the prognostic significance of CDK1 in various cancers, where the aberrant expression of CDK1 could play a dominant role in the tumor microenvironment." (PMID 36090896, 2022). "When initially described in the context of cancer, phosphorylation at S381 was also found to inhibit in vitro transformation, while cyclin-dependent kinase 1 (CDK1), a key driver of mitosis, phosphorylates YAP at three alternative residues, positively regulating oncogenesis in vitro." (PMID 35119068, 2022). "However, in kidney chromophobe (KICH), the expression of CDK1 in cancer tissues was significantly lower than that in the adjacent normal tissues." (PMID 36090896, 2022). "In these scenarios, CDK1 plays key roles in the progression of cancer and survival of cancer cells." (PMID 35806389, 2022). "In 25 cancer types, CDK1 showed an upregulated trend when comparing to normal tissues." (PMID 35693556, 2022). "CDK2 and CDK1 are vital in tumors and therefore attractive targets for cancer therapy." (PMID 35115540, 2022). "A poor clinical prognosis is observed in cancer patients with high CDK1 expression." (PMID 35681641, 2022).
cancer (continued). "Following the identification of M078 as the potential targeted drug for CDK1, it was hypothesized that M078 could inhibit the activation of CDK1, thereby restraining the proliferation of cancer cells." (PMID 36224755, 2022). "Therefore, the expression of CDK1 is closely correlated with the development and progress of various cancers including CCA, which makes it a potential promising target for molecular targeted therapy." (PMID 36568241, 2022). "Inhibiting CDK1 or CDK1-related signaling pathways could increase the efficacy of cancer treatment by overcoming immune or apoptotic resistance." (PMID 35681641, 2022). "Structure-based virtual screening indicated that amentoflavone may exert its potential anti-cancer effects via targeting cyclin B1/CDK1 complex which was further validated by in vitro experiments." (PMID 35484963, 2022). "Additionally, we used the Kaplan-Meier plotter database to assess the prognostic relationship of CDK1 expression with a range of cancer types." (PMID 36090896, 2022). "Moreover, CDK1 itself also was involved in multiple cancer development through inducing the phosphorylation of hTERT and the hTERT-mediated RNA dependent RNA polymerase (RdRP) activity." (PMID 36818671, 2022). "However, CDK1 inhibitors can prevent cell division and promote cancer cell apoptosis and tumor regression." (PMID 35406786, 2022). "On the contrary, CDKN3 was reported as a tumor suppressor in some cancers as it is a negative regulator of Cyclin-dependent kinases (CDK1 and CDK2) but the exact effect of CDKN3 in cancer cell proliferation, either enhancing or precluding, it cannot be explained by its CDK regulation, alone." (PMID 35446856, 2022). "Given that CDK5 expression is dispensable in these cells, whereas CDK1, 2, 7, and 9 are common essential genes required for the proliferation of almost all cancer cells lines, the effects of Roscovitine are highly likely to be attributable to inhibition of CDK5." (PMID 35514210, 2022). "CDK1 activity is dysregulated frequently in various cancers." (PMID 35330393, 2022). "Similarly to CCNA2, overexpression of CCNB1 and CDK1 has been detected in several human cancers, including PDAC." (PMID 36359879, 2022). "FAM111B, ZWINT and CDK1 have been shown to play important roles in the development of many cancers." (PMID 35406786, 2022). "Studies have proved that CDK1 is a poor prognostic biomarker of LUAD and that increased expression of CDK1 may lead to a high risk of cancer recurrence and a poor prognosis in patients with LUAD." (PMID 36419898, 2022). "The CDK1 gene is also related to several other cancer diseases." (PMID 35632527, 2022). "Meanwhile, CCNB1, CCNB2, and CDK1 are highly expressed in almost all cancer types, which may play an important role in cancer." (PMID 34337056, 2021). "CDK1 plays a key role in the control of the eukaryotic cell cycle by modulating the centrosome cycle as well as mitotic onset, and deregulation of CDK1 is considered a promising future cancer treatment." (PMID 33591950, 2021). "Moreover, the cancer cell cycle progression is promoted when ROS inhibits phosphatase Cdc14B resulting in the activation of cyclin-dependent kinase 1 (Cdk1)." (PMID 33922139, 2021). "CDK1 is a serine/threonine kinase that is often dysregulated in human cancers including GC." (PMID 33962568, 2021). "Furthermore, alterations in the associated genes (CDK-1, CDK-4, CCNE1, CDKN2A, RBI, NCAPG, AURKA, and CCND2) were determined in five CRC studies (CRC, TCGA, Firehose, CRC, TCGA, Nature, CRC, Pan-Cancer, MSKCC and CPTAC-2)." (PMID 33732631, 2021).